CFTR (CF transmembrane conductance regulator)
Diseases named in the same sentence as CFTR in open-access papers (continued):
Sharing a sentence is not in itself a finding about the gene and the disease.
infection (continued). "When we further examined bacterial burden, we observed an increase in CFTR-depleted embryos at 2 dpi when compared to wild-type infection, which was greatly increased by 4 dpi." (PMID 32850470, 2020). "Specifically, time of addition assays and the assessment of the exposure of VP2/VP3 minor capsid proteins indicated a role for CFTR during BKPyV transport to the endoplasmic reticulum, an essential step during the early stages of BKPyV infection." (PMID 32229236, 2020). "It has previously been shown that expression of mature CFTR to the apical membrane decreases upon infection with P. aeruginosa bacteria, even in cells that were pre-treated with CFTR correctors (VX-809 or VRT-325)." (PMID 32092967, 2020). "Further, although infections are reduced on CFTR modulator treatment 5, 6, chronic infection remains a consistent feature 7, indicating a continued need for novel approaches to the treatment of bacterial infections in CF." (PMID 33303916, 2020). "Further investigation is warranted to find the as yet unidentified molecular basis and to delineate the differential role of the CFTR/ROS axis in both epithelial inflammation and immunity to infection, and the link with CF phenotype in patients." (PMID 32849617, 2020). "Mabs-infected CFTR-depleted ZF rapidly succumb to infection, reflecting a hypersusceptibility to this mycobacterium in CF, providing a first glimpse into CFTR-mediated host defenses to Mabs infection." (PMID 30759393, 2019). "Numerous mammalian models have been generated to investigate the role of CFTR dysfunction in innate immunity and hypersusceptibility to infections." (PMID 30759393, 2019). "In summary, we demonstrate that CFTR dysfunction leads to hypersusceptibility to Mabs infection in vivo, potentially explaining the high rates of infection seen clinically in CF patients." (PMID 30759393, 2019). "Herein, using CFTR-depleted ZF larvae as an innovative vertebrate model that recapitulates important aspects of the CF immuno-pathogenesis, we elucidated the role of CFTR in regulation of innate immunity to Mabs infections." (PMID 30759393, 2019). "Overall, these results suggest CFTR is required for early and late neutrophil recruitment to localized Mabs infection and to control the intracellular growth of Mabs." (PMID 30759393, 2019). "At later stages, however, CFTR ablation triggers a hyper-inflammatory response following infection with Mabs, with qRT-PCR revealing upregulation of tnfa expression, especially after infection with the R form, similar to findings reported previously in mice." (PMID 30759393, 2019). "For many years, the main CF treatment strategies were focused on the downstream effects of CFTR dysfunction, such as airway obstruction, infection and inflammation." (PMID 31921811, 2019). "Exposure to CS alone or infection with either R5- or X4-tropic HIV by itself suppressed CFTR mRNA and function." (PMID 29789655, 2018). "CF management not only requires CFTR correction and modification but intensive symptomatic treatment targeting inflammation, infection, bronchial hydration and nutrition." (PMID 28449677, 2017). "As soon as 10 min following infection, CFTR competent BMDMs are able to internalize bacteria, whereas BMDMs isolated from either Cftr−/− or CftrF508del/F508del or CftrF508del/− mice exhibited a major internalization defect." (PMID 28079883, 2017). "Under these circumstances increased Tat expression or de novo infection of bronchial epithelial cells leading to disruption of bronchial epithelial integrity, decreased ciliogenesis and inhibition of CFTR biogenesis and function." (PMID 28060951, 2017). "The extent of lung similarities between humans and ferrets includes comparable submucosal gland expression of CFTR within the serous tubules, important for the secretion of fluids and mucus into the lung and for protection of the airways from infection." (PMID 27340661, 2016).
infection (continued). "In contrast, cystic fibrosis transmembrane conductance regulator (CFTR)-associated pathways, cell cycle processes (S-phase and others), and DNA damage processes were all downregulated following infection." (PMID 27677841, 2016). "In this study, differences in TNF- α, CXCL1/KC, and lung histology were compared between CFTR–/– mice and WT-mice after 24 hours of infection with highly mucoid Sp strain CHB756." (PMID 26469863, 2015). "Infections with the three strains in CFTR–/– mice produced very different results with in both BAL and lung." (PMID 26469863, 2015). "In a variety of human cell lines, caveolin-2 forms a heterodimer with caveolin-1, which after infection with P. aeruginosa, co-localizes with CFTR and P. aeruginosa." (PMID 26047157, 2015). "Clearly, additional studies are required to determine if P. aeruginosa, and or infection with other bacteria such as Acinetobacter that reduces CFTR abundance, suppresses the efficacy of VX-809 + VX-770 in vivo." (PMID 26018799, 2015). "Infection of HT-29 cells with a lentiviral vector harbouring shRNAi targeting CFTR resulted in the knockdown of CFTR mRNA and protein by 88 % and 69 % respectively." (PMID 26549988, 2015). "In contrast, infection of Caco-2/15 cells with a lentiviral vector carrying shRNAi against CFTR resulted in a 52 and 39 % reduction in CFTR gene and protein expression respectively when compared to scrambled-infected cells." (PMID 26549988, 2015). "Second, higher TGF-β production early in infection will further inhibit CFTR-mediated Cl− secretion by HET respiratory epithelial cells and also induces IL-6 production by HET AMs." (PMID 25840995, 2015). "Higher CFU recovery and shorter survival were observed following infection of CFTR–/– mice with CHB756 compared to infection with CHB1126, WU2, or CHB1058 (P≤0." (PMID 26469863, 2015). "This is further supported by decreased IL-33 expression when CFTRdelF508 AECs are pre-treated with a CFTR corrector (VX-809) and/or potentiator (VX-770) before infection." (PMID 26793709, 2015). "CFTR deficiency in mice results in the upregulation of CD95, crucially involved in aseptic inflammation, bronchial cell death rate, and susceptibility to infection." (PMID 26770018, 2015). "The factors that promote the development of infection are complex but include the abnormal composition of the airway lining fluid as a consequence of abnormal expression of the CF transmembrane regulator protein (CFTR)." (PMID 25883282, 2015). "Miglustat, a well-characterized iminosugar-based inhibitor of β-glucosidase 2 (GBA2), has shown promise in CF treatment because it reduces the inflammatory response to infection by P. aeruginosa and restores F508del-CFTR chloride channel activity." (PMID 25141135, 2014). "Media from F508del CFTR monolayers had 3.5 × 106 fold higher RSV titers relative to infected wt CFTR cells (p = 0.000009) on day 2 post infection." (PMID 24056672, 2013). "Peak viral yield was achieved within 48 h of infection in the F508del CFTR transduced cells, and decreased over time." (PMID 24056672, 2013). "In this context, it remains to explore if the inhibition of CFTR function modifies macrophage physiology that can led to alteration of its function and thus to chronic inflammation and infection." (PMID 24098711, 2013). "In CF, dysfunction of the CF transmembrane conductance regulator (CFTR) results in impaired muco-ciliary clearance leading to an environment favorable for infection and inflammation which ultimately destroys the lung." (PMID 24086277, 2013). "In this work, we considered CF vs non-CF macrophages in order to determine differences in their functions related to chronic inflammation/infection and the impact of CFTR pharmacological inhibition." (PMID 24098711, 2013). "Infection efficiency was an order of magnitude higher in cells expressing misfolded Cystic Fibrosis Transmembrane Conductance Regulator (CFTR) mutant proteins than in cells expressing the correctly folded protein." (PMID 21625534, 2011).
infection (continued). "Following infection, S9 cells expressing CFTR experienced an increase in intracellular ceramide concentrations whereas IB3-1 CFTR-defective cells did not." (PMID 21490807, 2011). "Kaplan Meier analysis was performed to assess the effect of CFTR genotype upon the age at which the infection was acquired for 13 organisms." (PMID 20932301, 2010). "Subjects with minimal CFTR function acquired infection at a younger age than those with residual function for 12 of 13 organisms (p-values ranging: < 0.001 to 0.017)." (PMID 20932301, 2010). "Multivariate Cox regression was used to assess the relationship of CFTR genotype with acquisition of infection using each of these different definitions as the primary outcome." (PMID 20932301, 2010). "If this is the case in humans, then alteration in CFTR function should correlate with infection with a variety of respiratory pathogens." (PMID 20932301, 2010). "Regardless of mechanism, the findings of this study indicate that reduced CFTR function leads to a global disruption of infection control and acquisition." (PMID 20932301, 2010). "To address these issues, we evaluated the correlation between CFTR genotype and infection with a variety of pathogens using detailed infection data collected by the U.S. CF Twin and Sibling Study (CFTSS)." (PMID 20932301, 2010). "It has been demonstrated that CFTR recruitment in detergent resistant micordomains participates in the regulation of the cell response to infection and inflammation." (PMID 19893743, 2009). "Beside the decreased Cl− permeability, the misfolded F508del-CFTR is partially retained in the ER where it activates UPR which can be enhanced by infection and inflammation." (PMID 20041182, 2009). "Personalized approaches that integrate anti-inflammatory therapies, mucoregulatory agents, and possibly CFTR modulators may offer improved outcomes by simultaneously targeting infection, inflammation, and epithelial dysfunction." (PMID 40732035, 2025). "This suggests that acute models of infection, even in the presence of functional CFTR, may have relevance for CF disease." (PMID 40422262, 2025). "Here, we define a mechanism by which the prevalent commensal P. melaninogenica enhances host defense against S. aureus in a TLR2 dependent manner which requires functional CFTR, indicating P. melaninogenica as an immune modulatory bacterium capable of altering pathogen infection dynamics." (PMID 41198444, 2025). "When the channel is not functional, as it happens in CF patients, dysfunctional CFTR leads to a dehydrated airway surface layer and buildup of sticky mucus eventually leading to growth of pathogenic bacteria and infection." (PMID 41070403, 2025). "MCP-1 and CXCL10 are classically know as monocyte chemokines; however, there is evidence from murine infections studies that they also contribute to neutrophil chemotaxis and were also found to be significantly increased in CFTR-/- samples compared to WT controls." (PMID 39903773, 2025). "Thus, while secondary factors such as infection and inflammation undoubtedly amplify oxidative stress in CF, a primary, CFTR-driven oxidative insult appears to be a crucial initiating event." (PMID 40573184, 2025). "Moreover, infection impaired adenylate cyclase signaling and CFTR-mediated ion transport, providing mechanistic insight into virus-induced secretory diarrhea." (PMID 41284734, 2025). "However, it should also be noted that PwCF on CFTR modulator therapies maintain chronic infections and acquire new infections, despite having CFTR function restored." (PMID 40422262, 2025). "These in vitro findings using infection-naïve macrophages support the hypothesis that intrinsic CFTR-related abnormalities in macrophage signalling pathways contribute to the generation of inflammation in CF airways." (PMID 39903773, 2025).
infection (continued). "Therefore, future studies assessing the impact of CFTR modulators on the hyperinflammatory immune response to infection should focus on CF mouse strains in which, for example, the human F508del mutation has been modelled." (PMID 39903773, 2025). "Similarly to SARS-CoV-2-infected CFTR WT cells, CFTR KO cells showed a moderately well-developed ER, rich in ribosomes on the outer surface and extensive dilatations increasing with the time of infection." (PMID 38892373, 2024). "Additionally, although some studies have demonstrated a reduction in airway inflammation and infection with CFTR modulators, other studies have reported substantial residual inflammation and infection, at least to levels similar to those observed in NCFBE." (PMID 39293854, 2024). "It has been discussed that the CFTR genotype may correlate with infection and the pathogenicity of certain pathogens, potentially interfering with treatment with CFTR modulators." (PMID 39728371, 2024). "Overall, it is evident that the absence of functional CFTR in macrophages acts as a regulator influencing many biological processes associated with the bacterial clearance and effective infection resolution." (PMID 39606224, 2024). "N protein-expressing cells were present in both cell lines 24 h post-SARS-CoV-2-infection onwards, although the positivity was more pronounced in WT than in CFTR-KO cells at all time points analyzed, in line with the reduced viral load measured in the extracellular milieu." (PMID 38892373, 2024). "By contrast, CF carriers, who still express ACE2, but have only one normal CFTR gene, may therefore be more likely to have severe COVID than normal subjects who begin infection with normal levels of CFTR and ACE2." (PMID 39043712, 2024). "Furthermore, IAV M2 protein was proven to be crucial for CFTR degradation during infection, as either siRNA-based M2 knockdown or inhibition of M2 activity abolished M2-induced degradation of CFTR." (PMID 38731896, 2024). "Thus, 24 h of infection with P. aeruginosa can enhance F508del CFTR mRNA levels, protein maturation, and function in CF airway epithelial cultures." (PMID 37998353, 2023). "SMM is composed of both infectious byproducts and inflammatory factors; the contribution of infection versus inflammatory factors in enhancing CFTR function in HBE cells can be compared using a bacterial–epithelial co-culture model versus adding SMM to HBE cultures." (PMID 37998353, 2023). "The Tppp − / − mouse offers a model system to understand the consequences of a CFTR-independent perturbation in this pathway and to test directly the impact of a potential modifier of CF airway disease severity on airway inflammation in response to infection." (PMID 37507487, 2023). "Finally, it is possible infection persists after ETI because established infections become autonomous of primary (i.e., CFTR-mediated) or secondary (i.e., lung damage–mediated) host defense defects of CF." (PMID 36976651, 2023). "It is of paramount importance to understand if lung infection and biochemical profiles continue to change with time on ETI in a predictable manner as studies of previously approved CFTR modulators showed a resurgences of pathogen infection after the period of initial improvement." (PMID 38104128, 2023). "In addition to experiments on CFTR regulation and CFTR function, 16HBE14o− cells are frequently used as a model to study infection and the innate immune response in airway disease." (PMID 37269165, 2023). "Deciphering the molecular mechanism linking CFTR dysfunction to Vav3 overexpression and the subsequent formation of fibronectin adhesion platforms will pave the way for alternative approaches with which to tackle the infection-prone phenotype of CF lungs." (PMID 36602863, 2023). "For example, longstanding infection can induce an immune-tolerant state that dampens antibacterial responses to pathogens and tolerance could persist after CFTR function is improved." (PMID 36976651, 2023).
infection (continued). "PwCF with G551D CFTR mutations showed a decrease in P. aeruginosa in sputum samples during the first year of taking VX-770/Kalydeco; however, infection is not eradicated and pathogen burden subsequently rebounded at 6 and 12 months after an initial decline." (PMID 37998353, 2023). "In the case of the respiratory tract, non-functional CFTR responds to thick mucus that clogs the bronchi and bronchioles, promotes infections caused by bacteria, and causes chronic inflammation leading to lung damage and respiratory failure." (PMID 37259341, 2023). "It is of paramount importance to understand if lung infection and biochemical profiles continue to change with time on ETI in a predictable manner, because studies of previously approved CFTR modulators showed a resurgence of pathogen infection after the period of initial improvement." (PMID 37841851, 2023). "This may orient the selection of specific antibiotics to treat infection in combination with CFTR modulators." (PMID 36625583, 2023). "However, after 12 hours, infection of CF+CFTR cell monolayers with CO or GE induced significant disorganization and, in areas, a total lack of ZO-1 between cells that was similar when compared to CF cell monolayers." (PMID 37680748, 2023). "Another limitation is that peripheral blood cells were obtained from healthy donors and not CF patients, whose neutrophils and monocytes can be affected by the CFTR mutation even in the absence of infection." (PMID 37284754, 2023). "The pattern of expression of airway surface liquid (ASL) homeostasis-associated genes (CFTR, BPIFA1, MUC1, MUC5AC, MUC5B) in the PCLS varied greatly between the three strains, and only infection with strain T15 induced statistically significant changes in this group of genes." (PMID 38276150, 2023). "Non/dysfunctional CFTR compromises several aspects of neutrophil function in response to infection." (PMID 35408875, 2022). "Therefore, our data demonstrate that pretreatment of CF macrophages with CFTR modulators is more effective in enhancing B. cenocepacia clearance than post-infection treatment." (PMID 35252032, 2022). "CFTR modulators might thus affect the development of chronic airway infections and/or improve the status of existing infections in CF patients." (PMID 35406809, 2022). "CFTR–/– mice treated with PA-LPS (20 μg/mouse) were used as a model for CF-inducedlung infection." (PMID 35148101, 2022). "Abnormal CFTR function impairs host defense, mucociliary clearance, and microbicidal activity in the airways; moreover, dysfunctional immune cells contribute to an impaired response to infection." (PMID 35315363, 2022). "Absence of functional CFTR results in imbalanced osmotic equilibrium and subsequent mucus build up in the lungs-which increases the risk of infection and eventually causes death." (PMID 35327663, 2022). "Interestingly, pre-infection treatment with CFTR modulators in the presence of glycine decreased B. cenocepacia CFUs more efficiently than post-infection treatment did." (PMID 35252032, 2022). "Other disadvantages are that rAd-mediated CFTR expression in post-mitotic airway epithelial cells is transient and that rAd infection promotes strong cellular and humoral immune responses, which cause the destruction of transduced cell, as well as prevent repeated dosing." (PMID 36304167, 2022). "Many of the studies conducted use small cohorts and, as shifts in established microbial communities often take some time, global longitudinal studies would more accurately represent the impact of CFTR modulators on the airway microbiome and consequently infection." (PMID 35408875, 2022). "Thus, rehydrated CFTR-KD cells were protected from infection despite normally intense bacterial growth." (PMID 35563895, 2022).